ENSG00000286224 (novel protein)
Synonyms: LOC128092249
Gene: Protein-coding gene on chromosome 21 (46,326,288 to 46,326,491, forward strand). Ensembl gene ENSG00000286224.
Genetic constraint (gnomAD): Loss-of-function variants: 4 observed, 3.3 expected, observed/expected ratio (o/e) 1.21, 90% interval 0.56 to 1.9. That is too few expected variants to judge how well the gene tolerates losing a copy. Missense variants: 85 observed, 66.83 expected, observed/expected ratio (o/e) 1.27, 90% interval 1.07 to 1.52. Synonymous variants: 25 observed, 26.21 expected, observed/expected ratio (o/e) 0.95, 90% interval 0.69 to 1.33.